PROX1 (prospero homeobox 1)
Diseases named in the same sentence as PROX1 in open-access papers (continued):
Sharing a sentence is not in itself a finding about the gene and the disease.
brain tumors (4 papers, 2011 to 2017). "However, a recent publication shows that PROX1 expression is associated with a higher grade in astrocytic gliomas, the most common brain tumour type in adults." (PMID 21970873, 2011). "PROX1 is the mammalian homologue of the Drosophila homeobox protein Prospero, which acts as a brain tumour suppressor by inhibiting neuroblast self-renewal." (PMID 21970873, 2011). "In addition, PROX1 has been ascribed suppressive as well as oncogenic roles in several human cancers, including brain tumors." (PMID 27626492, 2016). "Hence, like in fruit-flies and possibly in human brain tumours, Prox1 might confer mammalian glia with proliferative potential." (PMID 26709696, 2015).
intestinal tumor (4 papers, 2010 to 2016). "We have recently shown that Prox1 is essential for the expansion of the stem cell pool in intestinal tumours, where its deletion reduced the number of stem cells." (PMID 27731315, 2016). "We analyzed Prox1, a stem cell regulator in intestinal tumors that promotes the transition from benign to a malignant phenotype by oncogenic Wnt/ß-catenin signaling." (PMID 27811361, 2016). "New data evidenced that the appearance of Prox1 is the hallmark of the transition from benign colon adenoma to malign carcinoma, and over expression of Prox1 promotes intestinal tumor progression." (PMID 23675176, 2010).
Kaposi's sarcoma (4 papers, 2017 to 2022). A malignant neoplasm characterized by a vascular proliferation which usually contains blunt endothelial cells. "Furthermore, the vast majority of Kaposi sarcomas seem to be PROX1-positive, while its expression in cases of angiosarcoma reaches 50%." (PMID 35885529, 2022). "Therefore, the regulation of PROX1 expression by KSHV is a key event in transforming a KSHV-infected MSC to Kaposi’s sarcoma." (PMID 34492084, 2021). "However, G-protein signaling (RGS) 4 is not expressed in LECs, as Kaposi sarcoma-associated herpes virus upregulates PROX1, which is involved in LEC differentiation, leading to the downregulation of RGS4." (PMID 36067135, 2022).
liver fibrosis (4 papers, 2020 to 2023). "The established markers of LyECs (Prox1, Pdpn, Ccl21a, Mmrn1, Reln, and Rassf9) are highly expressed in hepatic LyECs from CCl4-induced liver fibrosis, NASH and BDL mice." (PMID 36632228, 2023). "Our transcriptome sequencing results showed decreased Prox1 expression in the LyECs of liver fibrosis mice." (PMID 36632228, 2023). "Recent studies identified that hedgehog signalling promoted prospero homeobox protein 1 (PROX1) expression in liver fibrosis, which inhibited HIF‐1α ubiquitination via a deubiquitinase called ubiquitin specific peptidase 19 (USP19)." (PMID 35187072, 2021). "In summary, these data provided that curcumol had mitigated hepatic fibrosis and inhibited pathological angiogenesis, and the hedgehog signalling pathway and PROX1 are involved in this progress." (PMID 32119185, 2020). "On the other hand, studies have found that Prospero Homeobox 1 (PROX1) can inhibit the expression of HIF-1α: CCl4-induced liver fibrosis mice, curcumin inhibits LSECs angiogenesis by regulating the Glis-PROX1-HIF-1α signaling pathway, thus slowing down the development of liver fibrosis." (PMID 33933107, 2021). "Our transcriptome sequencing results also showed decreased Prox1 expression in LyECs from liver fibrosis mice, and the expression of the tight junction proteins ZO-1 (Tjp1) and Esam in LyECs was downregulated after liver fibrosis, which indicated that the permeability of hepatic LyECs was affected." (PMID 36632228, 2023). "Activation of Hh signalling could exacerbate mouse liver fibrosis and pathological angiogenesis via increasing the levels of HIF‐1α and VEGF‐A; meanwhile, it has a positive effect on PROX1 expression." (PMID 32119185, 2020).
lymphoma (4 papers, 2008 to 2020). A malignant (clonal) proliferation of B- lymphocytes or T- lymphocytes which involves the lymph nodes, bone marrow and/or extranodal sites. "A detailed immunofluorescence analysis of consecutive sections using costaining against CD30 or CD68 with Prox1, a marker for lymphatic endothelial cells, revealed the absence of lymphatic vessels in L428 CAM lymphomas." (PMID 31825135, 2020).
oral cancer (4 papers, 2014 to 2022). "Some proangiogenic factors have been reported in the development of lymphangiogenesis in oral cancer, such as prospero homeobox 1, forkhead box C2, and astrocyte elevated gene-1." (PMID 33668218, 2021).
papillary thyroid cancer (4 papers, 2016 to 2019). "It was previously reported that restituting the Prox1 expression in a cell line originating from papillary thyroid carcinoma, BcPAP, reduces cell proliferation." (PMID 29371975, 2017). "In papillary thyroid carcinoma, PROX1 inactivation has been shown to promote malignant tumor behavior." (PMID 29371975, 2017). "Altered Prox1 expression has been found in a variety of human cancers, including papillary thyroid carcinoma (PTC)." (PMID 29371975, 2017). "Moreover, whereas in PTC (papillary thyroid cancer) derived cell lines the PROX1 transcript level was negative or negligible in all three FTC derived cell lines (FTC-133, CGTH and ML1 tested by us), the PROX1 mRNA was present at different level." (PMID 31060342, 2019).
AIDS (3 papers, 2012 to 2018). A syndrome resulting from the acquired deficiency of cellular immunity caused by the human immunodeficiency virus (HIV). "Sections from ten AIDS-associated KS patients were double-stained for PROX1 and MMP14." (PMID 29934628, 2018). "Genetic variation rs17762192, upstream of PROX1, a negative regulator of IFN-γ expression in T cells, was associated with slower progression to AIDS (P = 6.2 x 10-7)." (PMID 22920050, 2012). "Although this SNP upstream of PROX1 was not genome-wide significantly associated with slower progression to AIDS, the loci could be replicated in an independent population of 590 HIV-infected seroconverters." (PMID 22920050, 2012).
angiosarcoma (3 papers, 2018 to 2022). A malignant tumor arising from the endothelial cells of the blood vessels. "LAS can be differentiated from other angiosarcomas in dogs based on expression of Prospero-related homeobox gene-1 (PROX-1) or lymphatic vessel endothelial receptor-1 (LYVE-1)." (PMID 34746271, 2021). "In angiosarcomas (primary or secondary), certain morphological features characterizing lymphatic differentiation, such as a hobnail cell appearance and kaposiform architecture, correlate with immunopositivity for D2-40, PROX1, and VEGFR-3." (PMID 35885529, 2022). "Notably, the vascular tumors from our models did not express PROX1 and did not have associated lymphatic effusions, indicating that these tumors were most likely angiosarcomas rather than lymphangiosarcomas." (PMID 29872503, 2018).
Chylothorax (3 papers, 2020 to 2022). The presence of chyle in the thoracic cavity. "While 70% of Prox1+/- embryos display edema and die at birth due to chylothorax and chylous ascites, we extracted chyle from the abdominal cavity of surviving Prox1+/- pups and used it in our in vitro study." (PMID 35663931, 2022). "The pulmonary tissues of a patient, born with HLHS, aortic arch hypoplasia, and valvular anomalies and developed postoperative chylothorax after aortic arch, and supravalvar aortic stenosis repair was stained for PROX1, PODOPLANIN, VEGFR2, and VEGFR3." (PMID 34590077, 2021).
colonic adenomas (3 papers, 2010 to 2022). "Positive staining is also observed in colon adenoma samples, whereas the highest PROX1 levels are seen in the severe dysplastic areas." (PMID 35885529, 2022). "Pathological studies in colon adenomas and adenocarcinomas revealed high PROX1 expression in the majority of the cases, whereas, in the areas of colon adenomas with severe dysplasia, high PROX1 levels were combined with accumulated β-catenin protein, implicating an activated Wnt signaling pathway." (PMID 35885529, 2022).
glaucoma (3 papers, 2017 to 2023). Increased pressure in the eyeball due to obstruction of the outflow of aqueous humor. "One of the causes of glaucoma is the dysfunction of Schlemm’s canal (SC) endothelial cells whose property resembles lymphatic endothelial cells due to Prox1 expression." (PMID 32357159, 2020). "Indeed, reduction in AHO simultaneously downregulated Prox1 and Klf4 expression compared with control eyes, proposing Prox1 as an accurate biosensor for SC functionality, which might be used for the early detection and prevention of glaucoma in humans." (PMID 37091974, 2023).
hemangioma (3 papers, 2015 to 2025). A benign vascular lesion characterized by the formation of capillary-sized or cavernous vascular channels. "KSHV was found in the lymphoid cells of MCD, as well as in the microvenular hemangioma, the pathognomonic endothelial lesion, positive for CD34, CD31, LYVE-7 and Prox-1, that characterizes this syndrome." (PMID 25607954, 2015).
lung adenocarcinoma (3 papers, 2022 to 2025). A carcinoma that arises from the lung and is characterized by the presence of malignant glandular epithelial cells. "Our findings indicate that the expression mechanisms of REST and/or PROX1 will help elucidate the transformation of lung adenocarcinomas into NECs." (PMID 35094211, 2022). "We examined the expression of p-AMPK, PROX1 and Ser79 phosphorylation in HCC (n = 90) and lung adenocarcinoma (n = 90)." (PMID 36433955, 2022).
non-small cell lung carcinoma (3 papers, 2024 to 2025). A group of at least three distinct histological types of lung cancer, including non-small cell squamous cell carcinoma, adenocarcinoma, and large cell carcinoma. "The expression profile and clinical relevance of PROX1 in non-small cell lung cancer (NSCLC) remain poorly defined." (PMID 40843762, 2025). "Notably, PROX1 remains largely unexplored in soft tissue sarcomas and non-small cell lung cancer, representing a significant gap in the current literature." (PMID 40843762, 2025). "Despite these limitations, our study identifies a potentially important prognostic role of PROX1 in resectable non-small cell lung cancer, and provides a foundation for future prospective investigations incorporating molecular profiling, standardized follow-up, and multicenter validation." (PMID 40843762, 2025). "Ev-packaged circTLCD4-RWDD3 is taken up by human lymphatic endothelial cells to promote the transcription of lymphangiogenesis factor Prospero homeobox 1 (PROX1) and promote lymphangiogenesis and lymphatic metastasis in non-small cell lung cancer." (PMID 39366930, 2024).
renal cell carcinoma (3 papers, 2014 to 2025). "We evaluated the expression of PROX1 in renal cell carcinoma cell lines, including 786-O, 769-P, OS-RC-2 and ACHN, as well as the human renal proximal tubular epithelial cell line HKC." (PMID 24797520, 2014). "However, the role of PROX1 in the development of renal cell carcinomas (RCCs) has not yet been studied." (PMID 24797520, 2014).
rhabdomyosarcoma (3 papers, 2019 to 2025). A rare aggressive malignant mesenchymal neoplasm arising from skeletal muscle. "Our previous studies have demonstrated that PROX1 plays a regulatory role in the myogenic phenotype in both skeletal myoblasts and rhabdomyosarcoma (RMS) cells." (PMID 41249736, 2025). "Moreover, the transcription factor PROX1 has been shown to be highly expressed in rhabdomyosarcoma." (PMID 35128576, 2022). "Of these genes, several may be important for rhabdomyosarcoma, including a homeobox transcription factor (PROX1), a tumor suppressor (CD82), a transposable element (PDBD5), a muscle sodium channel (SCN4A), and a long intergenic non-coding RNA (LINC00689) (see Discussion)." (PMID 31480361, 2019).
small cell lung carcinoma (3 papers, 2017 to 2025). Small cell lung cancer (SCLC) is a highly aggressive malignant neoplasm, accounting for 10-15% of lung cancer cases, characterized byrapid growth, and early metastasis. "PROX1 is linked to the aggressiveness of several epithelial cancers and neuroendocrine differentiation of small cell lung cancer." (PMID 40454483, 2025). "Next, we sought to determine whether PROX1 plays a role in maintaining the NEPC phenotype once it is established and promoting NEPC cell survival as has been described in small cell lung cancer." (PMID 40454483, 2025).
anemia (2 papers, 2010 to 2013). A reduction in the number of red blood cells, the amount of hemoglobin, and/or the volume of packed red blood cells. "Upon Prox1 overexpression in blood endothelial cells, late stage embryos display significant edema and anemia at E14.5." (PMID 23341894, 2013).
astrocytomas (2 papers, 2011 to 2016). "In contrast, PROX1 protein expression correlated with survival in 34 IDH-mutant high-grade astrocytomas." (PMID 27626492, 2016). "In this study we explored the correlation between PROX1 expression and patient survival in high-grade astrocytomas." (PMID 27626492, 2016). "To obtain a representative group of IDH-mutant high-grade astrocytomas for PROX1 protein analysis, we collected the IDH1 immunopositive (mIDH1R132) and IDH-mutated 1p19q non-codeleted tumors in our TMAs." (PMID 27626492, 2016). "Our results are of clinical importance and warrant the implementation of PROX1 in future trials of adults with IDH-mutant astrocytomas to further establish its role as a prognostic biomarker and potential treatment target." (PMID 27626492, 2016). "The aim of the present study was to determine the prognostic impact of PROX1 in high-grade astrocytomas." (PMID 27626492, 2016). "In the present study we have unraveled the role of PROX1 as a prognostic factor for patients with high-grade astrocytomas." (PMID 27626492, 2016). "Oligoastrocytomas showed a mean of 17.7%, astrocytomas of 16.5%, gemistocytic astrocytomas of 10.6% and oligodendrogliomas of 12.5% PROX1 immunopositive tumour cells." (PMID 21559010, 2011). "The potential role of PROX1 as a pathway-specific biomarker for astrocytomas is discussed." (PMID 27626492, 2016). "Alternatively, and based on our previous findings in diffuse low-grade gliomas, PROX1 may be a prognostic marker for IDH-mutant astrocytomas that have progressed from pre-existing low-grade tumors." (PMID 27626492, 2016). "In conclusion, the transcription factor PROX1, with a widespread role in CNS development, is a prognostic marker for IDH-mutant high-grade astrocytomas that evolve through multi-step genetic alterations over time." (PMID 27626492, 2016). "We have recently shown that PROX1 protein is overexpressed in human astrocytic tumours, with highest levels in grade III and IV astrocytomas." (PMID 21559010, 2011). "The diverting roles of PROX1 in IDH-mutant and IDH-wildtype astrocytomas may be related to different epigenetic regulatory mechanisms between these tumor types." (PMID 27626492, 2016). "We conclude that PROX1 is a new prognostic biomarker for 1p19q non-codeleted high-grade astrocytomas that have progressed from pre-existing low-grade tumors and harbor IDH mutations." (PMID 27626492, 2016). "Whether PROX1 is a lineage-specific prognostic marker (i.e. for astrocytomas but not for oligodendrogliomas) is still unknown and needs to be studied further." (PMID 27626492, 2016).
atherosclerosis (2 papers, 2020 to 2024). A disease characterized by the build-up of fatty material and calcium deposition in the arterial wall resulting in partial or complete occlusion of the arterial lumen. "However, female Prox1-CreERT2+Panx1fl/flApoe-/- mice showed enhanced progression of atherosclerosis compared to Panx1fl/flApoe-/- controls of the same sex." (PMID 39775604, 2024). "The reason being, the wild type SUMO binds to prospero homeobox protein 1 (PROX1) and represses hepatic RCT genes, however, the SUMOylation deficient LRH1 fails to interact with PROX1, derepressing the RCT genes and reducing atherosclerosis in the mice." (PMID 33099299, 2020).
breast angiosarcoma (2 papers, 2018 to 2022). A malignant vascular neoplasm arising from the breast. "The deregulation of marker genes, including podoplanin (PDPN), prospero homeobox 1 (PROX-1), vascular endothelial growth factor 3 (VEGFR3) and endothelin receptor A (EDNRA), suggests that the radiation-associated breast angiosarcomas developed from radiation-stimulated lymphatic endothelial cells." (PMID 29515789, 2018). "Interestingly, radiation-induced breast angiosarcomas have their own transcriptome signature, with a panel of deregulated marker lymphatic genes such as PROX1, podoplanin, VEGFR3, and EDNRA, which allows its discrimination from primary breast angiosarcomas." (PMID 35885529, 2022). "They observed, specifically, in radiation-induced breast angiosarcomas a concrete deregulation in the marker genes of the lymphatic endothelial cells, such as podoplanin (PDPN), PROX1, VEGFR3, and endothelin receptor A (EDNRA), which was probably induced through chronic oxidative stress." (PMID 35885529, 2022). "Interestingly, the dysregulation of PROX1, along with PDPN, VEGFR3, and EDΝRA, seems to play a pathogenetic role in the development of post-radiotherapy breast angiosarcomas, which, through the identification of those specific genes, present a discriminating genetic “signature”." (PMID 35885529, 2022).
breast tumor (2 papers, 2021 to 2023). "In agreement, survival analysis of patients using the Kaplan–Meier plotter web tool associated high levels of Prox1 expression in breast tumors with increased survival rates." (PMID 37508533, 2023). "We also showed here that Prox1 expression is reduced in breast tumors as compared to normal tissue and that Prox1 correlates with a favorable prognosis in patients." (PMID 37508533, 2023). "Most importantly, over-expression of Prox1 inhibited breast tumor growth in vivo in both heterotopic and orthotopic xenograft mouse models." (PMID 37508533, 2023). "Similarly, examination of the data form cBioPortal database further confirmed the reduction in Prox1 expression in all different subtypes of breast tumors as compared to healthy tissue." (PMID 37508533, 2023). "Also, using the TNM plotter web tool to examine a larger number of datasets, we showed a similar reduction in Prox1 expression in breast tumor samples (Figure 1Β)." (PMID 37508533, 2023). "Subsequently, we wanted to test whether Prox1 was able to inhibit breast tumor growth in an orthotopic xenograft mouse model, which better mimics the original tumor microenvironment." (PMID 37508533, 2023). "Studies showed that the expression of PROX-1 in breast tumor cells could reduce the MMP14-dependent invasiveness of the tumor cells, and PROX-1 may be a suppressor gene in breast tumor cells." (PMID 35054174, 2021).
carcinoma in situ (2 papers, 2015 to 2022). "Experiments on mice have shown that PROX1 is a specific target of the β-catenin/TCF pathway, playing an essential role in the transition from benign colon adenoma to carcinoma in situ by affecting cell adhesion and polarity." (PMID 35885529, 2022).
Cirrhosis (2 papers, 2020 to 2022). A chronic disorder of the liver in which liver tissue becomes scarred and is partially replaced by regenerative nodules and fibrotic tissue resulting in loss of liver function. "Meanwhile, we found that the expression level of PROX1 of LyECs in the ACLF group decreased to 61% of that in the cirrhosis group." (PMID 35629036, 2022). "In addition, the violin plotting of PROX1 showed that the expression level of PROX1 of LyECs in the ACLF group decreased to 61% of that in the cirrhosis group." (PMID 35629036, 2022).
hemangioendothelioma (2 papers, 2014 to 2020). A vascular proliferation characterized by the presence of prominent endothelial cells and the formation of vascular channels. "PROX1 participates in the transition from benign colon adenoma to carcinoma, and in mouse hemangioendothelioma cells, stable overexpression of PROX1 induces an invasive phenotype and promotes expression of genes involved in cell migration." (PMID 24797520, 2014).